MGAT1 (alpha-1,3-mannosyl-glycoprotein 2-beta-N-acetylglucosaminyltransferase)
Diseases named in the same sentence as MGAT1 in open-access papers (continued):
Sharing a sentence is not in itself a finding about the gene and the disease.
lipid metabolic disorders (1 paper, 2018). "Although results indicate that the metabolic mechanism of lipid regulation by MGAT1 and MOGAT3 was altered, evidence of association between lipid metabolic disorders caused by aberrant expression of MGAT1/MOGAT3 and PCa are lacking." (PMID 29692867, 2018).
multiple sclerosis (1 paper, 2013). A progressive autoimmune disorder affecting the central nervous system resulting in demyelination. "Exceptional PD-related examples of seemingly active miRNA-spliced transcripts predicted interactions include USP13, which promotes smooth (SMO) signaling by preventing its ubiquitination, RGS3 which contributes to neural progenitor/stem cell regulation and MGAT1, involved in multiple sclerosis." (PMID 23717260, 2013).
neuropathic pain (1 paper, 2021). Chronic pain caused by damage to nerve fibers. "γ-Aminobutyricacid (GABA) transporters 1 and 4 (mGAT1 and mGAT4) have been increasinglyrecognized as promising drug targets for neuropathic pain (NP) associatedwith imbalances in inhibitory neurotransmission." (PMID 34347423, 2021).
nonalcoholic steatohepatitis (1 paper, 2015). "Thus, although reducing intrahepatic lipid content will most likely protect the liver from the development of nonalcoholic steatohepatitis (NASH), inhibition of TAG synthesis by MGAT1 inhibition may not necessarily be beneficial, at least in mice." (PMID 28943619, 2015).
prostate tumor (1 paper, 2012). "Here we have introduced MGAT1 shRNA into human HeLa cervical and PC-3-Yellow prostate tumor cells lines, generating cell lines with reduced transcript, enzyme activity and branched N-glycans at the cell surface." (PMID 22957033, 2012).
schizophrenia (1 paper, 2017). A major psychotic disorder characterized by abnormalities in the perception or expression of reality. "Recently, protein levels of important glycosylation enzymes, B3GNT8 and MGAT4A, were found decreased in the prefrontal cortex in schizophrenia (12 case–control pairs), whereas in our study B3GNT1, B3GNT3 and MGAT1 transcripts were downregulated in schizophrenia cases." (PMID 28418402, 2017).
soft tissue sarcoma (1 paper, 2019). A malignant neoplasm arising from muscle tissue, adipose tissue, blood vessels, fibrous tissue, or other supportive tissues excluding the bones. "Clinical data from the GEPIA dataset confirms that CDK4, CCT2, and MGAT1 expression levels are highly correlated with prognosis, and that up-regulation may lead to a significant reduction in survival time in patients with soft tissue sarcoma." (PMID 32117430, 2019).
Teratozoospermia (1 paper, 2018). "Disease categories impacted in 22 and 23 dpp Mgat1 cKO germ cells include Teratozoospermia and Asthenozoospermia diseases of men." (PMID 29386567, 2018).
triple-negative breast carcinoma (1 paper, 2025). An invasive breast carcinoma which is negative for expression of estrogen receptor (ER), progesterone receptor (PR), and human epidermal growth factor receptor 2 (HER2). "Overexpression of MGAT1 leads to immune evasion due to aberrant elevation of CD73 membrane translocation, which suppresses CD8+ T cell function, especially in immune-cold triple-negative breast cancer (TNBC)." (PMID 40229283, 2025). "Here, the authors show that MGAT1 modulation of CD73 glycosylation and function regulates tumor immune response in triple-negative breast cancer." (PMID 40229283, 2025).
tumor (19 papers, 2012 to 2025). "Dysregulated MGAT1 caused uncontrolled accumulation of CD73 on the tumor plasma membrane that elevates levels of adenosine, leading to suppression of CD8+ T cell function and subsequent tumor immune evasion." (PMID 40229283, 2025). "Among these genes, CDK4, CCT2, and MGAT1 were associated with overall survival and recurrence-free survival, and the expression levels of these three genes were significantly higher in tumor tissues." (PMID 32117430, 2019). "To further validate the role of the MGAT1-CD73 axis in immune checkpoint blockade responses, we conducted gain- and loss-of-function experiments in MGAT1-KD, MGAT1-OE, and CD73-4NQ tumor models." (PMID 40229283, 2025). "MGAT1 OE in tumor cells conferred resistance to immune cell-mediated cell death, whereas tumor cells with KD of MGAT1 were more vulnerable to immune cell-mediated killing." (PMID 40229283, 2025). "We then took an unbiased approach to delve into MGAT1 protein expression within tumor cells and its correlation with CD8+ T cell presence, employing multiplex immunohistochemistry." (PMID 40229283, 2025). "MGAT1 affects tumor progression and improves prognosis by regulating macrophage glycosylation levels." (PMID 40565574, 2025). "MGAT1 expression and glycosylation are lower in tumor tissues than in normal tissues, correlating with tumor progression and poorer prognosis in PDAC." (PMID 40164585, 2025). "We identified MGAT1, a critical glycosyltransferase, as an inhibitory tumor immune regulator whose overexpression drives tumor immune evasion in TNBC." (PMID 40229283, 2025). "A significant increase in both the tumor size and tumor weight was observed 25 days post-injection of the MGAT1-OE tumor cells." (PMID 40229283, 2025). "To evaluate the role of MGAT1 in tumor growth in vivo, we created murine cell lines with modified MGAT1 expression." (PMID 40229283, 2025). "Conversely, the MGAT1 knockdown significantly enhanced the efficacy of anti-PD-L1 therapy, characterized by reduced tumor progression." (PMID 40229283, 2025). "We also found that MGAT1 OE in tumor cells enhanced a tumor-promoting M2-like phenotype in TAMs, usually defined by the expression of CD163 and MHC II." (PMID 40229283, 2025). "Using multiomic spatial analyses and experimental validation, we identify MGAT1, a glycosyltransferase, as a pivotal factor governing tumor immune response." (PMID 40229283, 2025). "The interactome of MGAT1, resolved through mass spectrometry, identified several tumor immune-responsive proteins, including antigen-presenting proteins such as HLA-A and HLA-B, as well as CD73." (PMID 40229283, 2025). "Focusing on the reduced MGAT1 expression in tumor regions, we analyzed the interaction between MGAT1-Macrophages and monocytes, mediated by the SERPINA1_LRP1 ligand-receptor pair." (PMID 39081317, 2024). "More importantly, the protein expression level of MGAT1 was also lower in tumor tissues compared to normal tissues." (PMID 39156890, 2024). "To delve deeper into the disparities in MGAT1 gene expression between tumor and normal tissues, we analyzed TCGA bulk datasets for enhanced visualization." (PMID 39081317, 2024). "Our assessment revealed a strong correlation between MGAT1 expression and macrophage infiltration within tumor samples." (PMID 39081317, 2024). "In tumor tissues, MGAT1 expression was lower than in normal tissues, not only in macrophages but also in RNA-seq data." (PMID 39156890, 2024). "Specifically, MGAT1 expression in macrophages is significantly lower in the tumor group compared to the normal group." (PMID 39156890, 2024). "The results indicated that patients with low expression of MGAT1-positive macrophage marker genes had better prognoses, suggesting that lower MGAT1 expression in macrophages correlates with better tumor prognosis." (PMID 39156890, 2024).
tumor (continued). "This detailed analysis unravels the complex spatial cellular interactions within the tumor microenvironment, highlighting the potential role of MGAT1-Macrophages and monocytes in the context of HCC." (PMID 39081317, 2024). "Third, our research focused on the impact of MGAT1 on macrophage function and tumor prognosis, with less emphasis on other glycosyltransferase genes." (PMID 39156890, 2024). "Immunohistochemical assays comparing healthy liver sections with hepatocarcinoma tissues highlighted the elevated presence of MGAT1 in tumor matrices." (PMID 39081317, 2024). "Multiple transcriptomic data were comprehensively analyzed to explore the role of glycosylation processes in tumor progression, and functional experiments were performed to assess the effects of MGAT1 overexpression on PDAC cell proliferation and migration." (PMID 39156890, 2024). "Future research should further explore the specific mechanisms of MGAT1 in tumor progression and develop targeted therapeutic strategies to improve the prognosis and treatment outcomes of PDAC patients." (PMID 39156890, 2024). "A similar pattern was observed in paired sample comparisons, where tumor specimens consistently exhibited higher MGAT1 expression than their normal counterparts." (PMID 39081317, 2024). "We performed transfection experiments to overexpress MGAT1 in tumor cells and confirmed it using PCR." (PMID 39156890, 2024). "This analysis revealed a significant increase in MGAT1 expression in tumor samples compared to normal tissues." (PMID 39081317, 2024). "This analysis led to the identification of genes generally associated with cancer cells (MUC1, LGALS3, UGDH, TSTA3, and GALE) or the stromal compartment (LGALS1, PSAP, LGALS9, IDS, and MGAT1) in most of the tumor types analyzed." (PMID 38384845, 2024). "We observed that the glycosyltransferase-related gene MGAT1 is highly expressed in macrophages in the normal group but is lowly expressed in the tumor group." (PMID 39156890, 2024). "Stable overexpression of the MGAT1 gene in the Huh7 cell line resulted in a significant increase in tumor growth rate in severe combined immunodeficiency (SCID) mice." (PMID 32117430, 2019). "Further in vitro and in vivo experiments also show that overexpression of MGAT1 can play a role in tumor progression." (PMID 29310626, 2018). "These experiments clearly indicate visible differences in tumor sizes 3–4 weeks after the injection of MGAT1 overexpressing Huh7 cells into the mice." (PMID 29310626, 2018). "Knockdown of Mgat5 in mice, as well as Mgat1 knockdown in cells, results in a decrease in tumor incidence, growth and metastasis." (PMID 24040379, 2013). "To begin exploring the role of MGAT1, we generated human tumor cell lines stably expressing MGAT1 shRNA, and achieved ∼70% suppression of branched N-glycans and the invasive phenotype, without altering proliferation and viability in cell culture." (PMID 22957033, 2012). "Furthermore, flow cytometry analysis further revealed similar immune suppression of T cells cocultured with MGAT1-OE tumor cells and hyperactivation of T cell activities with MGAT1-KD tumor cells." (PMID 40229283, 2025). "Notably, neoplasia patients exhibited a tendency to upregulate several glycogenes, including MGAT1, MAN2A1, MAN2B1, and MGAT2 (which contributed to the clustering), associated with the initial steps of the biosynthesis of more complex N-glycan structures." (PMID 40087977, 2025). "In addition, there was decreased fraction of Tim3+PD1+ and increased fraction of CD8+ T cells expressing a higher level of Ki67 in MGAT1 knockdown tumor-bearing mice compared to that in the control mice." (PMID 40229283, 2025). "Increased expression of MGAT1 induced by abnormal THSB1 causes severe accumulation of CD73 on the tumor surface that overproduces extracellular adenosine, extrinsically inhibiting CD8+ T cell function and promoting tumor evasion." (PMID 40229283, 2025).
tumor (continued). "The MGAT1 gene showed some correlation with the proportion of stromal cells in tumor samples." (PMID 39156890, 2024). "Besides its prognostic impact, MGAT1 is also an important tumor marker gene, with an AUC of 0.909 from ROC testing." (PMID 39156890, 2024). "N-acetylglucosaminyltransferases (MGAT1) regulated the tumour growth and invasion." (PMID 34539936, 2021). "A previous report confirmed that MGAT1 contributes to tumor migration and invasion." (PMID 32528944, 2020). "Recently, MGAT1 has also been proposed to play a substantial role in tumor immunity." (PMID 32143591, 2020). "Furthermore, the stable overexpression of MGAT1 gene in Huh7 cell lines lead to a significant increase in tumor growth rate in Severe Combined Immunodeficient (SCID) mice." (PMID 29310626, 2018). "Within this context, it is reasonable to suggest that MGAT1 overexpression can interfere with the regular proteoglycan synthesis mechanisms, and therefore, might have the potential to enhance tumor progression." (PMID 29310626, 2018). "To evaluate the importance of the physical interaction between MGAT1 and CD73 for tumor growth, we overexpressed both MGAT1 and CD73 WT (MGAT1 OE + CD73WT) or MGAT1 and CD73-4NQ (MGAT1 OE + CD734NQ) in 4T1 and E0771 murine TNBC cell lines." (PMID 40229283, 2025). "Specifically, we observed that genes participating in the N-glycosylation pathway such as MAN1A1, MGAT1, FUT8, and B4GALT3 were significantly upregulated in neoplasia when compared with healthy subjects." (PMID 40087977, 2025). "Intriguingly, ablation of MGAT1 significantly boosted immune cell infiltration into MGAT1-KD TNBC spheroids, whereas elevated expression of MGAT1 in tumor cells drastically suppressed the infiltration of immune cells in the MGAT1-OE TNBC spheroids." (PMID 40229283, 2025). "We further validated a positive correlation between MGAT1 and membrane CD73 expression in malignant epithelial areas across all regions per tumor using multiplexed immunohistochemistry (mIHC)." (PMID 40229283, 2025). "In summary, this study revealed a previously unidentified role for MGAT1 in regulating CD73 and its enzymatic activity to determine tumor immune suppression in the context of TNBC." (PMID 40229283, 2025). "Allogeneic killing triggered by L-PHA was reduced by lowering β1,6-branching both in tumor cells via MGAT5 deletion (clone B2) or in T cells via MGAT1 deletion." (PMID 41005308, 2025). "Inhibiting MGAT1 activity in vivo with compounds like W-GTF01 has demonstrated promising efficacy, particularly in immune-cold TNBC models, by promoting tumor regression through the revival of cytotoxic CD8+ T cell responses." (PMID 40229283, 2025). "Functional experiments showed that MGAT1 overexpression inhibits PDAC cell proliferation, migration, and invasion, suggesting its role as a tumor suppressor." (PMID 40164585, 2025). "Overexpression of MGAT1 significantly inhibited the proliferation and migration of PDAC cells and affected intercellular interactions in the tumor microenvironment." (PMID 39156890, 2024). "Furthermore, our GSEA analyses showed a correlation between high MGAT1 expression and increased THBS1 signaling activity, implying a cascade of THBS1-MGAT1-CD73 in maintaining a tumor-promoting immune microenvironment." (PMID 40229283, 2025). "Collectively, these results indicate that the glycosyltransferase MGAT1 acts as a crucial negative regulator of CD8+ T cells in immune-cold TNBC, whose accumulation could contribute to tumor immune evasion through suppressing cytotoxic IFNγ-secreting CD8+ T cell function." (PMID 40229283, 2025).
cancer (15 papers, 2012 to 2025). A tumor composed of atypical neoplastic, often pleomorphic cells that invade other tissues. "Future studies should further explore the role of MGAT1 in other cancer types and develop innovative therapeutic strategies targeting glycosylation pathways." (PMID 39156890, 2024). "Of interest, various anti-cancer compounds have been shown to cause ER stress and lower MMP levels, it is possible that the lack of MGAT1 expression leads to ER stress as glycosylated proteins build up in the lumen of ER." (PMID 32260356, 2020). "In order to visualize the possible interaction ofBRI3 isoforms with the candidate proteins MGAT1 andIFITM3, colocalization assay was performed in the Huh7hepatocellular carcinoma cell line." (PMID 30983867, 2018). "In N-glycans, the mannosyl (alpha-1,3-)-glycoprotein beta-1,2-N-acetylglucosaminyltransferase (MGAT) family of enzymes including MGAT1, MGAT4A, and MGAT5A are upregulated in many cancers, to fuel the loss of contact inhibition, increased cell motility, invasion, and metastasis." (PMID 39628991, 2024). "Mgat1 and Mgat5 were found to serve important roles in a number of cellular functions, including cell death and survival, protein synthesis, cellular movement, post-translational modification, protein degradation, and cancer." (PMID 36499281, 2022). "Our results demonstrate that blocking MGAT1 is a potential target for anti-cancer therapy." (PMID 22957033, 2012). "Although MGAT1 is required for mouse development beyond day E9.5, our results suggest that partial systemic depletion of MGAT1 in adults may be tolerable and have important anti-cancer effects." (PMID 22957033, 2012). "Furthermore, the access of T-synthase to the Tn antigen could be blocked either by an endogenous inhibitor, as observed for GnT1IP-L towards MGAT1, or by a Tn antigen-binding molecule presented in cancer cells." (PMID 30115016, 2018). "After 2D coculture, the impact of MGAT1 in regulating CD8+ T cell function that, in turn, influenced the cancer cell survival was measured by flow cytometry." (PMID 40229283, 2025). "In both the healthy and cancer glycocalyx, MGAT1, COSMC, and UGCG are critical chain initiating enzymes that synthesize N-linked glycans (complex and hybrid), O-linked glycans, and GSLs, respectively, and may play a crucial role in cell signaling, immune evasion, and cancer metastasis." (PMID 39628991, 2024). "The results showed that the expression of CDK4, CCT2, and MGAT1 in LMS tissues was significantly higher than that in adjacent tissues and an important member of the cancer signaling pathway." (PMID 32117430, 2019). "The distal 5q35.2q35.3 contains the homeobox MSX2, MGAT1 and BTNL3 respectively involved in embryonic development and cancer." (PMID 22253721, 2012). "While previous reports have consistently demonstrated that silencing MGAT1 can impede cancer cell progression and metastasis, the absence of MGAT1 inhibitors underscores the tremendous untapped therapeutic potential of MGAT1." (PMID 40229283, 2025). "Although loss of GnT-I (or mutations in MGAT1) are not common in NB or cancer, functional loss of GnT-I, here achieved by CRISPR/Cas9 knockout of MGAT1, is a highly efficient approach to produce cells or organisms greatly enriched in oligomannose N-glycans." (PMID 39742082, 2024). "The basal protein levels of MGAT1, along with a few other key proteins of cell proliferation were determined in various cell types, including carcinoma and non-carcinoma cell lines." (PMID 29310626, 2018). "Based on evaluation standards from multiple layers, W-GTF01 (No.8 compound) was confirmed as a potent inhibitor of MGAT1 activity and stimulator of CD8+ IFNγ-producing T-cell response, leading to lowest cancer cell survival." (PMID 40229283, 2025).
infection (5 papers, 2013 to 2025). The state of being infected such as from the introduction of a foreign agent such as serum, vaccine, antigenic substance or organism. "Slc35a1 KO led to complete resistance to MVM infection, while Mgat1 and Cosmc KO led to significant inhibition of infection." (PMID 37175850, 2023). "Besides, PPARγ, some of the critical enzymes involved in fatty acid biosynthesis, TAG biosynthesis, cholesterol esterification like Fasn, Dgat1, Dgat2, Mgat1, Acat1, Acat2, etc., showed a temporal increase in expression levels at the later time points post-infection." (PMID 41358489, 2025). "Either by using DMJ to inhibit the Golgi’s α-mannosidase I, knocking down MGAT1, or inhibiting the α-mannosidase II with swainsonine, infection was reduced in HEK but did not affect Vero cells." (PMID 35164559, 2021).